RICTOR (RPTOR independent companion of MTOR complex 2)
Diseases named in the same sentence as RICTOR in open-access papers (continued):
Sharing a sentence is not in itself a finding about the gene and the disease.
soft tissue sarcoma (1 paper, 2019). A malignant neoplasm arising from muscle tissue, adipose tissue, blood vessels, fibrous tissue, or other supportive tissues excluding the bones. "Use case – Soft tissue sarcoma with reported amplification ofKIT,PDGFRA,MDM2,RICTOR andFGF10." (PMID 31608148, 2019).
testicular cancer (1 paper, 2020). A primary or metastatic malignant neoplasm that affects the testis. "NDUFS1 has been reported to be under the regulation of RICTOR in testicular cancer patients." (PMID 32942548, 2020).
cancer (68 papers, 2012 to 2026). A tumor composed of atypical neoplastic, often pleomorphic cells that invade other tissues. "From the results, we found that 29 types of cancer exhibited abnormal RICTOR gene expression, 10 types of cancer exhibited RICTOR mutation dysregulation, and 9 types of cancer exhibited methylation dysregulation." (PMID 37372460, 2023). "Our findings indicate that RICTOR was overexpressed in twelve cancer types, and a high RICTOR expression was linked to poor overall survival." (PMID 37372460, 2023). "Next, we used functional enrichment analysis to evaluate the underlying molecular mechanisms of RICTOR in tumorigenesis and cancer development." (PMID 37372460, 2023). "Similar with immune-related genes, the transcription level of RICTOR is positively associated with most immune checkpoint genes in most cancer types except for GBMLGG and LGG." (PMID 37372460, 2023). "Some of these genes have been previously linked with HCC, including RICTOR, which was found to be dysregulated in cancers, including HCC." (PMID 34819028, 2021). "RICTOR has been found to be overexpressed and/or amplified in various other cancers and to cooperate with other driver mutations to stimulate cellular proliferation." (PMID 31393061, 2019). "mTORC2 also plays a role in cancer since the mTORC2 subunit RICTOR is also overexpressed in multiple cancer types and its overexpression increases mTORC2 activity which causes the cancer cells to become more proliferative and invasive." (PMID 25505994, 2014). "One of the well-known oncogenic alterations of the mTOR pathway is the RICTOR amplification, which has been shown to contribute to progression and metastasis in certain cancers through its association with the molecular signaling behind these processes (e.g., Wnt/β-katenin, MAPK/ERK pathways)." (PMID 38339294, 2024). "These analyses indicate that RICTOR is a valuable diagnostic biomarker in these cancer types." (PMID 37372460, 2023). "Therefore, the aim of this study was to comprehensively analyze the expression pattern, mutation status, methylation levels, prognostic value, and potential association between RICTOR expression and immune function in various cancers." (PMID 37372460, 2023). "Next, we studied the association between the RICTOR expression and patient prognosis to check whether it could be used as an early diagnostic biomarker for cancers." (PMID 37372460, 2023). "We investigated the correlation between RICTOR expression, genetic alteration, methylation and patient prognosis to check whether they could be used as an early diagnostic biomarker for cancers." (PMID 37372460, 2023). "Further experimental and clinical studies are needed to confirm these findings by elucidating the molecular mechanisms underlying the relationship between RICTOR and cancer, and to explore the practical application of RICTOR in cancer therapy and prognosis prediction." (PMID 37372460, 2023). "Interestingly, results from our study show only moderate impairment of tumor growth in vitro, which is in contrast to previous reports where mTORC2/RICTOR inhibition was associated with impairment of in vitro growth in several cancer entities." (PMID 28445935, 2017). "Amplification of RICTOR or elevated RICTOR protein expression is positively correlated with poor overall survival of cancer patients." (PMID 40934285, 2025). "Elevated expression of proteins and phosphoproteins of downstream of EGFR/ERBB in cluster #3 and #1 suggests EGFR/ERBB, SRC, c-RAF/MAPK, and PI3K/AKT/mTOR/RICTOR signaling as a major tumor-promoting circuits of these cancers." (PMID 40011822, 2025). "Meta-analysis of cancer genomics datasets shows the co-occurrence of RTK alterations with RICTOR overexpression in different cancer types." (PMID 40934285, 2025). "Database synthesis corroborated disease associations involving MTOR and its partners (e.g., TSC2, RICTOR, RPTOR, MLST8, AKT1 across selected carcinomas)." (PMID 41300706, 2025).
cancer (continued). "Several studies have demonstrated both RICTOR amplification and Rictor overexpression in different types of cancer, including lung cancer." (PMID 38339294, 2024). "Amplification of RICTOR has been reported in various cancer types, including approximately 10% of lung SCCs." (PMID 38706776, 2024). "To find the possible regulatory mechanism of mutation resulting in aberrant RICTOR expression, we also examined the alteration frequency of RICTOR in pan-cancer data." (PMID 37372460, 2023). "MHC genes had a co-expression with RICTOR in almost all cancer types, particularly in LIHC, ACC, BRCA, and GBM." (PMID 37372460, 2023). "We further demonstrated that the RICTOR expression was significantly influenced by genetic alteration and DNA-methylation in multiple cancer types." (PMID 37372460, 2023). "Next, we examined the relationship between RICTOR expression and cancer subtypes by the TISIDB database." (PMID 37372460, 2023). "In conclusion, our pan-cancer analysis shows that RICTOR has a high expression in various cancers, and its mRNA expression, mutation, and DNA methylation are significantly associated with patient survival in certain tumors." (PMID 37372460, 2023). "Given the upregulation in 12 cancer types, we investigated possible regulatory mechanisms of a high RICTOR expression using correlation analysis between mRNA expression, methylation and genetic alteration." (PMID 37372460, 2023). "In this study, we examined RICTOR’s molecular characteristics and clinical prognostic value by pan-cancer analysis." (PMID 37372460, 2023). "Although there is growing evidence supporting the important role of RICTOR in the tumorigenesis of specific cancer types, its mechanism of action in cancer remains poorly understood." (PMID 37372460, 2023). "Based on our results, we found that the higher expression of RICTOR was significantly correlated with poor patient survival in multiple cancer types, including CESC, LIHC, KICH, BRCA, COAD, OV, and LUAD." (PMID 37372460, 2023). "Our pan-cancer analysis highlights the critical role of RICTOR in tumor progression and its potential as a prognostic marker for various cancer types." (PMID 37372460, 2023). "Fifteen (11.9%) cancers harbored 16 PI3K pathway mutations: PIK3CA (n = 7), AKT2 and RICTOR (n = 3 each), PTEN, PIK3C2B, and PIK3R1 (n = 1 each)." (PMID 36124727, 2022). "In total, 24 of the 33 TCGA datasets (72.7%) exhibited statistically significant activation of RICTOR signaling in NFATc2-High cancers." (PMID 34021224, 2021). "Alterations in RICTOR have been identified in a number of cancer cell types, and its involvement in tumorigenesis and resistance to therapies has recently begun to be unraveled." (PMID 34680615, 2021). "Phosphorylated Prickle1 forms a complex with mTORC2 through binding RICTOR, and further activates mTORC2 to regulate focal adhesion and cancer cell migration." (PMID 32899613, 2020). "Currently, there are no relevant immune-related trials; however, based on the regulatory functions of RICTOR in different immune cells, it is a promising cellular target for cancer immunotherapy." (PMID 32041519, 2020). "Expression of the MAPKAP1 deletion decreased cell cycle and DNA replication gene expression in mutant Ras-dependent cancer cell lines, mirroring the transcripts specifically decreased when we knocked down either RICTOR or MAPKAP1 in the same cancer cells." (PMID 31497244, 2019). "RICTOR (rapamycin‐insensitive companion of mTOR) has been found to be overexpressed in various cancers (e.g., gastric and lung) and to be capable of cooperating with other driver mutations to stimulate cellular proliferation." (PMID 31393061, 2019).
cancer (continued). "In many cancer types, it was shown that RICTOR overexpression in tumoral cells leads to an increase in cell proliferation and survival, and a decrease in cell apoptosis in cancer cells as well as a remodeling of the stroma, which all favor tumor development." (PMID 29455662, 2018). "We summarize below the recent research into the biology of RICTOR signaling in cancers in which RTK signaling plays a major role." (PMID 29455662, 2018). "The correlation between RICTOR overexpression, tumor progression and poor survival in a variety of cancers suggests that RICTOR amplification plays a role on cell proliferation, cell survival or tumor microenvironment." (PMID 29455662, 2018). "Here, we summarize new research into the biology of RICTOR signaling in cancers focusing on tumors with altered RTK." (PMID 29455662, 2018). "The importance of the PI3K/AKT/mTOR pathway in cancer has been known for many years but the central role of RICTOR in this pathway is only starting to emerge." (PMID 29455662, 2018). "Several studies have demonstrated an amplification of the RICTOR gene or an overexpression of its protein in different cancer types." (PMID 29455662, 2018). "We show that, as a key signaling node and critical effector of RTKs, RICTOR is becoming a valuable therapeutic target in cancer with altered RTK." (PMID 29455662, 2018). "Alterations of RICTOR have been identified in a number of cancer cell types and its involvement in tumorigenesis has begun to be unraveled recently." (PMID 29455662, 2018). "Mammalian Target of Rapamycin complex 2 (mTORC2) and its regulatory component Rapamycin-insensitive companion of mTOR (RICTOR) are increasingly recognized as important players in human cancer development and progression." (PMID 28445935, 2017). "TERT, SDHA and RICTOR had the most frequent copy number gains (26.4%, 25.7% and 23.6% of all cases, respectively), with significant enrichment in carcinomas." (PMID 27873319, 2017). "Recent work has shown that various cancer cells have elevated mTOR activity due to upregulation of mTOR complex components, e.g., mTOR, RICTOR, RAPTOR, mSIN1, PRAS40, and DEPTOR." (PMID 25906254, 2015). "We previously found that expression levels of certain components of mTOR complexes, such as mTOR itself and RICTOR, are upregulated in various human cancers as a result of silencing of specific microRNAs." (PMID 25906254, 2015). "We also identified overexpression of scaffolding proteins that are traditionally involved in the AKT/mTOR pathway including IRS1, RICTOR, and GAB2, which have been implicated as oncogenic contributors in other cancer types." (PMID 25999352, 2015). "We computationally predicted PTPRF, PRKAR2B, MAP4K3, and RICTOR to be responsible for the cancer phenotype, and each of them was experimentally validated by means of cell death or migration assay." (PMID 26336805, 2015). "RICTOR, a scaffold protein of the mTORC2 complex, regulates AKT signaling and has been implicated in tumor progression and therapy resistance across multiple cancers." (PMID 42080921, 2026). "In addition, several genes of the parallel PI3K/AKT pathway were more frequently mutated in CDX2-suppressed cancers, with the differences for PTEN, MTOR, and RICTOR reaching significance." (PMID 39452477, 2024). "Next, we extended our investigation by analyzing the protein expression levels of RICTOR using a large-scale proteome dataset obtained from the Clinical Proteomic Tumor Analysis Consortium (CPTAC) database where 10 types of cancer have protein expression data of RICTOR." (PMID 37372460, 2023). "Therefore, it will be meaningful to select these cancer types for further exploration of RICTOR’s regulatory mechanisms." (PMID 37372460, 2023).
cancer (continued). "Therefore, we made use of the Cancer Dependency Map by focusing on the genes encoding the mTOR components MTOR, RPTOR, and RICTOR." (PMID 37642941, 2023). "Next, we investigated the genetic alteration of RICTOR in pan-cancer." (PMID 37372460, 2023). "Thus, we studied the methylation levels of RICTOR between normal and tumor tissues in pan-cancer data." (PMID 37372460, 2023). "The function of RICTOR in pan-cancer still needs to be systematically elucidated." (PMID 37372460, 2023). "Furthermore, we examined the impact of RICTOR on tumorigenesis and cell survival across different types of cancer cells using the DepMap CRISPR data." (PMID 37372460, 2023). "Our results indicate that an aberrant expression of RICTOR in these cancers may be attributed to the promoter methylation of RICTOR." (PMID 37372460, 2023). "Given that high expression levels of RICTOR are associated with poor prognosis in CRC75 as well as a variety of other cancers, our findings have clinical implications since therapeutic autophagy inhibition in cancer clinical trials is currently ongoing." (PMID 31383875, 2019). "RICTOR is therefore becoming an important actor in cancer diagnosis, prognosis and treatment." (PMID 29455662, 2018). "In addition, the RICTOR gene has recently been shown to be amplified in cancer, highlighting its role in cancer development and its potential as a therapeutic target." (PMID 29455662, 2018). "The importance of RICTOR downstream of RTK in cancer is highlighted by the fact that not only can alterations of RICTOR and RTK co-occur in some tumors, but also that RICTOR expression is essential to permit the oncogenic potential of RTKs such as HER2, PDGFR, or EGFR." (PMID 29455662, 2018). "Interestingly RTK alterations have also been identified in these tumors and analysis of the available databases through the cBioPortal for Cancer Genomics shows a tendency for co-occurrence of RICTOR and RTK alterations in these tumors (see TCGA Data Portal;." (PMID 29455662, 2018). "Hence, the mTORC2/RICTOR is an interesting novel target for anti-cancer therapy in patients suffering from PDAC." (PMID 28445935, 2017). "Among them, we further investigated the feedback mechanism implicating RICTOR, a scaffold protein from the mTORC2 complex, because it had been suggested that RICTOR could play a role in cancer." (PMID 26356562, 2015). "Thus, we further investigated the correlation between RICTOR expression and the cancer stemness." (PMID 37372460, 2023). "While RICTOR and ZFX showed similar expression in both normal and cancerous epithelial cells, UGCG expression was elevated in cancer cells compared to normal epithelial cells." (PMID 40934285, 2025). "In this context, herein, we have mapped the first step of the metabolite-cell signaling-gene regulatory circuit connecting ganglioside metabolism with cancer, controlled by the EGFR-mTORC2/RICTOR complex." (PMID 40934285, 2025). "Additionally, RICTOR amplification has been speculated to be responsible for the resistance against chemotherapy, tyrosine kinase inhibitors, and ICIs, leading to tumor progression in various types of cancer." (PMID 38706776, 2024). "IIPA found that SFPQ interacts with many important proteins, such as YY1, RTN4, RICTOR, HDACs, BMI1, and HNRNPC, which are important in the development of cancer." (PMID 35707369, 2022). "RICTOR, through cellular signaling downstream of receptor tyrosine kinase (PI3K/AKT/mTOR), is actively involved in cytoskeleton assembly, cancer invasion processes, proliferation, metastasis and poor prognosis." (PMID 36231068, 2022). "In 12 (36.4%) datasets, RICTOR was the top dysregulated upstream regulator as identified by IPA, demonstrating significant predicted signaling activation in all 12 cancer types." (PMID 34021224, 2021).
cancer (continued). "In cells, miR-185 suppresses cancer formation by inducing cell cycle arrest and apoptosis by targeting Ras Homolog-MTORC1 Binding (RHEB), RPTOR Independent Companion of MTOR Complex 2 (RICTOR), and AKT Serine/Threonine Kinase 1 (AKT1)." (PMID 34069740, 2021). "Spheroids were collected to evaluate the cancer stem cells (CSCs) markers, such as EPCAM, CD133, and CD24, in HMGB1/RICTOR manipulated cells using real-time PCR methods." (PMID 34916485, 2021). "Specifically, the characteristics of BIA indicate the dissociation between RICTOR and TMBIM6 through the regulation of TMBIM6-leaky Ca2+ and the resultant inhibition of AKT activation impeding cancer formation." (PMID 32782388, 2020). "Functional analysis revealed that the upstream regulators (RICTOR, KDM5A, MAP4K4, and TRAP1) were activated due to the aberrant expression of sperm proteins in the cancer group compared to fertile men." (PMID 32942548, 2020). "RICTOR plays an important role in the PI3K/AKT/mTOR signaling pathway, which is one of the most commonly activated pathways in human cancer." (PMID 30139386, 2018). "Some targets of miR-218, such as ROBO1, RICTOR, BIRC5 and LAMB3, have been reported to participate in many cancer signaling pathways, such as the ERK/MAPK, Wnt/β-catenin, and Notch pathways." (PMID 29717030, 2018). "Further, we showed that RICTOR regulates three transcription factors, like ZFX, CTCF, and ELF1, that can further regulate multiple genes/enzymes, including some from the sphingolipid and ganglioside pathways in a cell-type and cancer-context-dependent manner." (PMID 40934285, 2025). "Expression analysis revealed that RICTOR, UGCG, and ZFX were highly expressed in cancer cells." (PMID 40934285, 2025). "The authors also showed that a member of the mammalian target of rapamycin (mTOR) C2 complex, RICTOR, can bind to PRICKLE1 and that PRICKLE1-MINK1-RICTOR complex integrity is essential for AKT (protein kinase B, PKB) activation, focal adhesion regulation, as well as migration of cancer cells." (PMID 39727954, 2024). "Nonetheless, for patients with other cancer types, RICTOR genetic alterations did not lead to a significant change in OS." (PMID 37372460, 2023). "Further pan-cancer analyses show positive correlations between the expression of RICTOR and the top 10 interacting genes in the majority of cancer types, except for gene PRR5 with negative correlation." (PMID 37372460, 2023). "According to the results, strong positive correlations were found between RICTOR and most of the immune-related genes in multiple cancer types except for GBMLGG and LGG which show negative correlations." (PMID 37372460, 2023). "This revealed that MTOR, and to a lesser extent RPTOR and RICTOR, are indispensable for the survival of the majority of cancer cell lines, regardless of MYC amplification status." (PMID 37642941, 2023). "Notably, expression levels of proteins facilitating mitochondrial-ER interaction, including AKAP1, RICTOR, Rab32, PACS2, GPR75, and PEMT1, were reduced in these cancer tissues." (PMID 33614647, 2021). "Interestingly, we also show that seven major gene regulators (TP73, RICTOR, NUPR1, NKX2‐3, MYCN, IL10, and EPO) involved in inflammation, oxidative stress, DNA damage, and cancer processes were affected by MP radiation." (PMID 29786969, 2018). "The role of these AKT-independent activities of RICTOR/mTORC2 in cancer development is not completely clear yet and will need to be validated." (PMID 29455662, 2018). "In contrast, RICTOR blockade led to significant reduction of constitutive IL-8 secretion from cancer cell lines, whereas no induction of IL-8 upon incubation with DFX was found (data not shown)." (PMID 28445935, 2017).